SOCS3 (suppressor of cytokine signaling 3)
Diseases named in the same sentence as SOCS3 in open-access papers (continued):
Sharing a sentence is not in itself a finding about the gene and the disease.
asthma (continued). "Resolution of eosinophilic inflammation is a critical goal for asthma therapy, and the promotion of a phenotype switch in eosinophils through SOCS3 down-regulation could be a possible strategy to achieve this goal." (PMID 25764157, 2015). "Therefore, as we demonstrated in the mouse model of allergic asthma treated with SOCS3 siRNA intranassally, SOCS3 up-regulated expression in asthma has to be controlled, in this case by gene silencing in order to restore SOCS3 homeostatic levels." (PMID 25764157, 2015). "The objective of this study was to evaluate if delivering of SOCS3 short interfering RNA (siRNA) intranasally in lungs could be a good therapeutic approach in an asthma chronic mouse model." (PMID 24637581, 2014). "Moreover, 2 of the miRNA that appeared downregulated after the SOCS3-siRNA therapy (miR-146b and 126) have been previously involved in asthma disease." (PMID 24637581, 2014). "We therefore examined whether purified CD4 T cells (>98%) from patients with NAEB and asthma had higher levels of SOCS3 gene expression as consequence of the preferential development of Th2 cells." (PMID 21765854, 2011). "Additionally, GAL reduced JAK/STAT3 expression in acute kidney injury (AKI) model through modulation of NF-κB (p65) and IL-6/JAK2/STAT3/SOCS3 signals via α7nAChR and in experimental asthma model, α7nAChR exerted promising effects by inhibiting NF-κB/STAT3/SOCS3 signaling." (PMID 37429998, 2024). "Hence, synthetic liposomes containing SOCS3 is an emerging therapeutic approach that may be used for the treatment of patients with asthma." (PMID 34414402, 2021). "A large-scale asthma eQTL study of 1111 human lung tissues identified an eQTL within GSDMA that was a risk allele for asthma in the GABRIEL GWAS study, and created a network of relationships with eQTL and GWAS data that identified SOCS3 as a key asthma pathway." (PMID 28774304, 2017). "In experimental asthma model, α7nAChR exerted promising effects by inhibiting NF-κB/STAT3/SOCS3 signaling." (PMID 37429998, 2024). "The expression of total STAT3 was increased in both asthma models, and phosphorylated-STAT3 (p-STAT3) expression increased in the OVA + ozone group, whereas SOCS3 expression was reduced." (PMID 34760922, 2021). "The expression of IL-17A in the lung tissue of asthma patients and HCs showed a strong correlation with the expression of STAT3 and SOCS3." (PMID 34760922, 2021). "To further evaluate the effects of SOCS3 deletion, we generated an OVA-induced asthma mouse model and adoptively transferred DCs into the asthmatic mice." (PMID 32807859, 2020). "They include RBM42, STX5, and TRIM41 in asthma, CYP27A1, GM2A, LGALS9, SPI1, and NLRC4 in COPD, as well as ATF3, PPP1R15A, ZFP36, SOCS3, NAMPT, and GADD45B in IPF." (PMID 31952466, 2020). "To this extend, we here shown that SOCS-3 is transcriptionally downregulated in COPD and therefore shows an expression pattern in COPD reciprocal to that in asthma, in which the molecule was shown be upregulated." (PMID 24138793, 2013). "Expressions of SOCS3 and SOCS5 mRNA were analyzed by real-time quantitative PCR in peripheral CD4 T cells from adult patients with NAEB, asthma and healthy controls." (PMID 21765854, 2011). "Because the accumulation of eosinophils is a feature of both asthma and NAEB, we determined if eosinophils are able to transcribe and translate mRNA for SOCS3." (PMID 21765854, 2011). "Recently, it has been demonstrated that prostaglandins are capable of inducing SOCS3 expression; moreover, we have reported that PGE2 is present in lung from subjects with NAEB and asthma, diseases that are characterized by high eosinophil counts." (PMID 21765854, 2011). "For these reasons, we determined if eosinophils, the characteristic inflammatory cells of asthma and NAEB, are able to express mRNA and synthesize SOCS3 protein." (PMID 21765854, 2011).
asthma (continued). "SOCS3 also exhibited negative correlations with asthma, dilated cardiomyopathy, ECM-receptor interaction, hypertrophic cardiomyopathy, and olfactory transduction." (PMID 40760666, 2025). "Suppressor of silencing cytokine signaling 3 (SOCS3) weakens the functions of eosinophils, the key inflammatory cells in asthma, but in the present study, it did not correlate with the studied clinical factors." (PMID 35244877, 2022). "The expression of SOCS3 and STAT3 has been evaluated in airway inflammation in some animal models, but we are the first to observe their changes in the lung tissue of asthma patients." (PMID 34760922, 2021). "Similarly, the suppressor of cytokine signaling 3 (SOCS3) is a protein involved in negative regulation of STAT3, a Th17 cell differentiation stimulator, which is involved in asthma pathogenesis." (PMID 35096261, 2021). "These genes included RBM42, STX5, and TRIM41 in asthma, CYP27A1, GM2A, LGALS9, SPI1, and NLRC4 in COPD, ATF3, PPP1R15A, ZFP36, SOCS3, NAMPT, and GADD45B in IPF, LRRC48 and CETN2 in asthma-COPD, COL15A1, GIMAP6, and JAM2 in asthma-IPF and LMO7, TSPAN13, LAMA3, and ANXA3 in COPD-IPF." (PMID 31952466, 2020). "Transcriptional down-regulation of SOCS3 has been observed in COPD and asthma patients." (PMID 30935889, 2019). "SOCS1, but not SOCS3, mRNA expression levels were increased (approximately 8- to 9-fold) in unstimulated and uninfected primary human BECs from children with severe asthma compared with those in BECs from NANA control subjects." (PMID 25630941, 2015). "Among the top genes are ones that have been previously related to asthma (e.g., APOE, CHI3L1, EGR1, MYH11, OXTR, SERPINB2, SOCS3) and corticosteroid-resistant asthma (e.g., FOS) though not necessarily in humans or via changes of the ASM." (PMID 26207385, 2015). "The increased expression of SOCS3 in eosinophils from patients with NAEB and asthma compared with controls is probably due to factors that could regulate SOCS3 expression in these cells under disease conditions." (PMID 21765854, 2011). "The increase of SOCS3 expression in response to Th2 cytokines in healthy individuals is markedly greater than in those from asthmatic and NAEB patients, indicating that eosinophils from individuals with asthma and NAEB had impaired upregulation of SOCS3 after Th2 stimulation." (PMID 21765854, 2011). "T-cell SOCS3 mRNA levels are increased in asthmatic patients and correlate with IgE levels, but a functional role for SOCS3 in human asthma is unknown, and thus the role of SOCS proteins in asthma is unclear." (PMID 25630941, 2015). "SOCS3 (a negative transcription factor) may interact with STAT3 and be involved in the corticosteroid insensitivity of the T2-low asthma model." (PMID 34760922, 2021). "Following 48 h of incubation in medium containing SOCS3 siRNA or NT siRNA, the analysis revealed a reduced transcription of GATA3 in eosinophils from patients with asthma (n = 5) treated with SOCS3 siRNA, but not in those incubated with the negative control (p < 0.05)." (PMID 25764157, 2015).
viral infection (39 papers, 2008 to 2025). "While SOCS3 has been implicated in various viral infections, its regulatory role in PCV2 replication remains undefined." (PMID 40872795, 2025). "We previously demonstrated that forced SOCS3 expression completely suppressed gp130-mediated STAT3 activation and survival of cardiomyocytes, and that the hearts of SOCS3 transgenic mice exhibited markedly increased susceptibility to viral infection." (PMID 34292971, 2021). "It would be of considerable interest to therefore determine the role of elevated SOCS3 in the obese in their greater susceptibility to COVID-19, influenza, and other viral diseases in insulin resistant individuals." (PMID 33193390, 2020). "Manipulation of SOCS1 and SOCS3 should play a key role in viral infections, particularly those caused by viruses that are associated with respiratory diseases." (PMID 33193390, 2020). "In SOCS protein family, SOCS1, and SOCS3 are the most potent inhibitors of cytokine signaling, and SOCS3 has also been implicated in viral infections and autoimmune diseases." (PMID 30487798, 2018). "Viral infections cause the elevated SOCS3 expression, which inhibits leptin signaling." (PMID 29868503, 2018). "Since our results presented above exhibited that IL-6-activated STAT3 was inhibited by IAV-induced SOCS3 and knockdown of SOCS3 downregulated IL-6 during the viral infection, we asked whether elevated activity of STAT3 caused by silencing SOCS3 affected IL-6 expression." (PMID 31474976, 2019). "In particular, SOCS1 and SOCS3 have been implicated in the pathogeneses of several viral infections, as viral up-regulation of these host proteins may dysregulate host antiviral strategies and thereby assist virally-infected cells in evading immune destruction." (PMID 28182772, 2017). "SOCS1 and SOCS3 are increasingly recognized as central regulators of host immune responses during viral infections." (PMID 40844207, 2025). "The Mechanism of CMV Infection), the involvement of SOCS1 and SOCS3 in the signaling pathway during viral infection is well-documented." (PMID 39066272, 2024). "To assess the role of SOCS3 in viral infection, we devised an ex vivo assay in which this gene was silenced by shRNA in HEK293T-Angiotensin-Converting Enzyme 2 (HEK-ACE2) epithelial cells, followed by infection with two strains of SARS-CoV-2." (PMID 38238298, 2024). "The expression patterns of multiple stem cell markers in SOCS3-expressing NPCs are similar to the phenotype in HCMV-infected NPCs, indicating that SOCS3 contributes to cell fate alteration induced by viral infection." (PMID 36753521, 2023). "A previous study demonstrated that natural killer cell activity can be inhibited by IL-17A through SOCS3, which can interfere with tumorigenesis and viral infection." (PMID 35296090, 2022). "An important finding of the current and previous studies is that SOCS proteins are upregulated following viral infection; expression of SOCS1 or SOCS3 following viral infection promotes the replication of multiple viruses." (PMID 35774982, 2022). "To confirm the molecular expression of SOCS3 in human gastric cancer lines before viral infection, we performed immunocytochemical staining with an anti-human SOCS3 antibody." (PMID 33659045, 2021). "SOCS1 and SOCS3 mRNA levels were increased in the early stage of viral infection, accompanied with increased mRNA levels of IFNα and IFNβ." (PMID 32149091, 2020). "In our study, SOCS1 and SOCS3 were increased in the early stage of viral infection in RD cells infected with an increased titer of EV71, accompanied by increased IFNα and IFNβ." (PMID 32149091, 2020). "Further investigation showed that SOCS3 promoted virus infection by inhibiting interferon-induced STAT3 phosphorylation." (PMID 32149091, 2020).
viral infection (continued). "In previous studies, the NF-kappaB and MEK/ERK signaling pathways have been shown to contribute to the regulation of SOCS3 expression, and the role of the MEK/ERK signaling pathway in inducing SOCS3 expression during virus infection has rarely been reported." (PMID 31552199, 2019). "The accumulated data suggests that SOCS1 and/or SOCS3 can differentially affect the severity of viral diseases in a highly cell-type-specific manner, reflecting the diversity and complexity of herpesvirus infection and the ocular compartment." (PMID 31031749, 2019). "Altogether, the induced SOCS3 levels either in viral infection or hyperleptinemia state of over-nutrition directing to host immune dysfunction." (PMID 29868503, 2018). "Growing evidence suggests that SOCS1 and SOCS3 are important inhibitory modulators in limiting the inflammatory effect of interferon signaling during viral infection." (PMID 21901105, 2011). "RSV and RSV mutant virus infection of MLE-15 cells at 24 h pi was associated with IFNα, IFNβ and SOCS1 and SOCS3 mRNA expression." (PMID 18851747, 2008). "The higher SOCS3 protein expression following ΔG virus infection suggests that G protein expression reduces SOCS3 protein expression during RSV infection." (PMID 18851747, 2008). "Accumulated data indicate that SOCS1 and/or SOCS3 may have different effects on the severity of viral diseases depending on the type of cells." (PMID 36032295, 2022). "We knocked down SOCS1 and SOCS3 via shRNA in RD cells prior to viral infection." (PMID 32149091, 2020). "Taken together, these results reveal that SOCS3 might play a crucial role not only in suppressing IL-6/STAT3 signaling but also in feedback regulation of IL-6 expression during the viral infection." (PMID 31474976, 2019). "Indeed, the involvement of SOCS3 in the regulation of IL-6 expression was demonstrated by our in vitro and in vivo experiments showing that depletion of SOCS3 significantly reduced the viral infection-triggered expression of IL-6." (PMID 31474976, 2019). "In addition, several lines of evidence have suggested that SOCS3 plays important roles in immune and inflammatory responses based on the altered expression of SOCS3 after viral infection." (PMID 31474976, 2019). "More recently, hypermethylation of SOCS3 was shown to associate with a poor clinical outcome in HCC patients with HBV infection backgrounds but not that with HCV or no virus infection." (PMID 28404963, 2017). "Therefore, it is imperative to explore the detailed methylation status of SOCS3 in HCC with different virus infection backgrounds and the relationship between its methylation and clinicopathology." (PMID 26393582, 2015). "The rapid and strong SOCS3 induction could be involved in the IL-26 effect on virus infection by inhibiting the initial IFN response." (PMID 23875025, 2013). "SOCS1 and SOCS3 may promote virus infection by inhibiting IFN-induced STAT3 phosphorylation." (PMID 32149091, 2020). "However, disruption of IL-6-STAT3 signaling by IAV-induced SOCS3 results in an adaptive increase in IL-6 expression by host in response to the viral infection, which may lead to excessive production of IL-6 and promote lung damage." (PMID 31474976, 2019). "Therefore, the suppression of IL-6/STAT3 signaling by elevated SOCS3 induced by IAV might contribute to excessive production of IL-6 during the virus infection." (PMID 31474976, 2019). "However, the exact relationship between IL-6 and SOCS3, especially the induction and the functional involvement of SOCS3 in regulating IL-6 production during the viral infection, remains unclear." (PMID 31474976, 2019). "Moreover, the induced expression of SOCS3 and IL-6 was examined in vitro after the virus infection." (PMID 31474976, 2019).
viral infection (continued). "Here, we found that in MSC cocultures, IL‐6 induced the expression of SOCS3 in EC, a typically IL‐6‐regulated gene known to downregulate cellular responses to cytokines 31, and which we previously found to play a role in modification of neutrophil recruitment by viral infection." (PMID 28376564, 2017). "The antagonist, pJAK2 (1001‐1013), is a SOCS1 and SOCS3 inhibitor that binds to the KIR region, blocking their inhibitory activity in different viral infections, such as HSV‐1 and influenza A." (PMID 40844207, 2025). "We identified 31 differentially expressed circRNAs and 7 mRNAs (HSPA8, HSPA1B, EGR2, CXCR4, SOCS3, NOTCH3, and ZNF527) related to viral infection." (PMID 41471859, 2025). "The influence of EGb on inflammatory-associated genes expression that regulate innate immune response to viral infection and cytokine production, namely IRF-3, IRF-7, tetherin, SOCS1, SOCS3, NFKB1, p65, and MxA was also examined." (PMID 35631163, 2022). "Indeed, both Western blotting and immunofluorescence staining showed increased IKBα and decreased nuclear p65 form of NFκB in IAV-infected SOCS3-knockdown cell and lung of TG mice as compared to WT host, suggesting that silencing SOCS3 may result in a suppression of NFκB upon viral infection." (PMID 31474976, 2019). "In conclusion, here we provide novel evidence that IAV triggered robust expression of SOCS3, a negative regulator of IL-6-STAT3 signaling, in an IL-6-independent manner at the early stage of the virus infection." (PMID 31474976, 2019). "When PBECs from asthmatic subjects were treated with anti-TGF-β antibodies prior to virus infection, both SOCS-1 and SOCS-3 mRNA were significantly reduced at 48 h p.i., p = 0.031 and p = 0.016 respectively." (PMID 22970254, 2012). "This is not unexpected because SOCS proteins form part of a classical negative feedback loop that is time-dependent, thus RSV and RSV mutant virus infection of MLE-15 cells and IFNα, IFNβ and SOCS1 and SOCS3 mRNA expression was examined at 48 h pi." (PMID 18851747, 2008). "SOCS3 expression is induced by JAK–STAT-activating cytokines including erythropoietin (EPO) and granulocyte colony-stimulating factor (G-CSF), and by myocardial insults, such as viral infection, pressure overload, or ischemia." (PMID 34292971, 2021). "None of these limited studies focused in particular on the SOCS proteins, and the findings were not interpreted in the context of the role of SOCS3 in virus infection, as was done in the case of TGEV." (PMID 33193390, 2020). "It was observed that there was a significant reduction in the expression of SOCS3 mRNA in the early stage of viral infection treated with the NF-κB inhibitor compared with the noninhibitor-treated EV71-infected cells." (PMID 32149091, 2020). "We found that these supernatants failed to stimulate the SOCS3 expression, as compared with viral infection control (3 hpi)." (PMID 31474976, 2019). "This is consistent with the observations that mice lacking SOCS3 have a considerably higher survival rate after lipopolysaccharide challenge or exhibit a lower viral load after virus infection." (PMID 31474976, 2019). "In this study, the methylation status of two loci of the CpG island (CGI) in the SOCS3 promoter was quantitatively investigated, with particular attention to the change in methylation intensities in primary HCC tissues with different virus infection backgrounds." (PMID 26393582, 2015). "Apart from this similarity, different virus infection pathways owned their unique genes, with STAT1,RSAD2 and IRF9 in the influenza A pathway,IL-2RA,IL-2RB and CD40 in the HTLV-1 infection pathway, HCFC1, MAP3K7, SOCS3, IRF9, HMGN1, and FAS in the herpes simplex infection pathway." (PMID 35795668, 2022).
viral infection (continued). "It is possible to observe a process of evasion of the immune response, most likely mediated by viral infection, showing a decrease in the transcription of evaluated ISGs in DENV-2 infected cells compared with cells stimulated with IFN-λ and an increase in SOCS1 and SOCS3 genes." (PMID 26411318, 2015). "RSV and RSV mutant virus infection of MLE-15 cells induced different type I IFN and SOCS1 and SOCS3 mRNA expression patterns at 24 h and 48 h pi, a feature that may be linked to sequential RSV gene expression due to their promoter-proximal location in the genome." (PMID 18851747, 2008). "SOCS3, relative to GAPDH housekeeping reference, was not changed by either the treatments or virus infection at the 24 hr time point." (PMID 24098792, 2013). "Comparing time-points post-WT or ΔG virus infection, no significant (p < 0.05) changes in IFNα, IFNβ or SOCS1 mRNA expression were observed at 24 h pi or 48 h pi; however, SOCS3 mRNA expression was considerably decreased from 24 h pi to 48 h pi." (PMID 18851747, 2008).